COL1A1 (collagen type I alpha 1 chain)
Diseases named in the same sentence as COL1A1 in open-access papers (continued):
Sharing a sentence is not in itself a finding about the gene and the disease.
tumor (continued). "We observed the expected reduction in the trabecular bone volume in Col1a1-Krm2-transgenic NSG mice compared to NSG controls, but there was no further impact caused by the injection of tumor cells." (PMID 35158823, 2022). "COL1A1 staining of tumor cells did not change significantly in 4T1 and E0771 tumors, but in 67NR tumors, the deficiency diet led to a significant increase in COL1A1 expression as compared to the control and 100 IU+cal groups." (PMID 36230508, 2022). "Additionally, the COL1A1 and COL5A1 were highly expressed in PTC tumor samples than in contrast to neighboring healthy samples." (PMID 35530352, 2022). "Intriguingly, these observations were almost further validated by our real‐time qPCR results of five pairs of tumor and adjacent nontumor samples, such as COL1A1, MMP1, MMP10, CXCL8, and IL1B." (PMID 34821009, 2022). "Col1a1, Col1a2, Col2a1, Col3a1, and Col5a2, which were commonly found in normal ECM of mouse, pig, and human breast tissues, were also identified in tumor ECM in addition to Col4a2, Col5a1, Col6a1, Col6a2, Col6a3, and Col7a1." (PMID 36547361, 2022). "Remarkably, gene expression levels of COL1A1, COL5A3 and TGFB were upregulated (p < 0.05) after the treatment with DPT in Caco-2 cells, another common cell line used to reproduce the features of the tumoural bowel epithelium." (PMID 36012487, 2022). "However, it is unclear about the specific mechanism of COL1A1 in LGG and how it is related to tumor immunity." (PMID 35789341, 2022). "Bioinformatic studies have also shown that, regardless of the tumor type, Col1a1 acts as a cancer suppressor." (PMID 35801156, 2022). "Similarly, IHC staining showed the physical juxtaposition of COL1A1 and ITGA2 in tumor tissue from patient b, which exhibited marked atypia." (PMID 35322024, 2022). "Here, we detected a more than 4-fold increase in the osteoclast surface per trabecular or cortical bone surface in metastatic areas, and again this tumor cell influence was not affected by the Col1a1-Krm2 transgene." (PMID 35158823, 2022). "Additionally, another recent study shows that COL1A1 inhibition in glioma cells decreased CD68+ and IBA1+ macrophages/microglia within the tumor, decreased mesenchymal transformation, and inhibited tumor growth." (PMID 36186781, 2022). "Finally, performed qRT-PCR and western blot analysis in Lnc-408-engineered BC cells, we confirmed that MMP2, ITGB1, and COL1A1 exhibited significant and substantial changes in Hs578T, MCF-7 cells, and primary BC tumor cells." (PMID 34079084, 2021). "Among them, the expression of COL1A1, COL10A1, and COL11A1 were found to be particularly high in tumor tissues compared with normal counterpart; on the contrary, the expression of COL4A4, COL6A5 and COL14A1 was significantly lower in tumor tissues." (PMID 34199373, 2021). "Collagen type I α 1 (COL1A1) is the pro-α 1 chain of type I collagen protein, as an essential component of the ECM, involved in many biological processes including ECM remodeling, tumor cell adhesion and cell migration." (PMID 34356118, 2021). "To assess whether expression of these MMPs and collagen I in combination with LAIR-1 impacts survival, we performed bioinformatic analyses of tumor MMP1, MMP9, COL1A1 and LAIR1 mRNA expression using data from the TCGA database." (PMID 34691040, 2021). "These hub biomolecules of tumor stroma network, AR, GATA2, miR-124, TOR1AIP1, ESR1, EGFR, STAT1, miR-192, GATA3, COL1A1, may give crucial information about tumorigenesis." (PMID 33907495, 2021). "Analysis of bulk tumour mRNA displayed a strong correlation between ACTA2, a marker of MSCs, and matrix remodelling enzymes (MMP2), ECM proteins (VCAN, FN1, COL1A1), immunomodulatory molecules (Serpine1, CXCL12), innate immune cell markers (CD14, ITGAX) and adaptive immune cell markers (CD4)." (PMID 34885111, 2021).
tumor (continued). "Other significant DE genes with high FC(log2), unique to the study were INHBA, COL1A1, COL11A1, COMP, SFRP4 and SPP1, which were clustered in STRING network analysis and correlated with tumour-infiltrating immune cells in TIMER, suggesting a specific interaction pathway." (PMID 34824625, 2021). "In addition, gene expression in the primary tumor (T-TIS) was higher compared to control (N-TIS) for most genes (TGFβ1, COL1A1, COL3A1, ITGAV, ITGAX) (matched samples)." (PMID 33718208, 2021). "We confirmed that CST1 protein was expressed in a subset (8.31%) of COL1A1+ fibroblasts in tumor samples, but it was barely detectable (0.27%) in nonmalignant samples." (PMID 34921160, 2021). "It indicated that the COL1A1, IGF1, COL5A1, CXCL12, PTEN, and SPP1 were significantly differently expressed in EC tumor compared with those in normal samples (P = 4.93E−02, P = 5.24E−03, P = 2.83E−04, P = 1.58E−06, P = 2.11E−12, and P = 6.91E−13, respectively)." (PMID 32641130, 2020). "In 7801 tumor tissues, ASPH also showed a positive correlation with RUNX2 as well as COL1A1." (PMID 33015050, 2020). "Also, the human PSCs were activated by the co-cultured mouse tumour cells as indicated by increased ACTA2, COL1A1, FN and TGFB1 mRNA levels." (PMID 32460715, 2020). "In this study, COL1A1 and FN1 were all ECM genes with elevated mRNA levels in tumor stromal cells." (PMID 30237810, 2018). "The disparity in the copy number of the fusion gene would result in different growth rates in distinct subclones, and subclones with higher copy numbers of the COL1A1-PDGFB fusion gene would expand faster than other subclones, dominating the primary tumor mass." (PMID 28977029, 2017). "Apart from that no other associations were observed between COL1A1, PRPF40A or UCP2 mRNA expression and patients’ gender, age, survival, smoking history, TNM classification, and tumour histology and differentiation." (PMID 28258342, 2017). "Hence, HCC cells with fibroblast-like characteristics facilitated rigid cell-cell adhesion and cell-COL1A1 interaction and thereby enhanced CAM-DR in tumor spheroids." (PMID 28423507, 2017). "The expression levels of ADARB1 (P<0.01), ADRB2 (P<0.05) and ANKRD1 (P<0.05) were significantly down-regulated in stage I LUAD tissues; COL1A1 (P<0.05) and MMP13 (P<0.05) were significantly up-regulated in stage I LUAD tissues compared with adjacent non-tumor tissues." (PMID 28881680, 2017). "Moreover, COL1A1 expression was unrelated to clinicopathological parameters, while COL1A2 expression was positively related to tumor size and depth of invasion." (PMID 27894325, 2016). "Notably, COL1A1 and FN1 are among the most highly expressed genes in the activated stroma subtype, suggesting tumor-promoting roles of activated CAFs." (PMID 27528027, 2016). "Treatment with celecoxib significantly decreased the induced tumor size and metastasis of the PyMT/Col1a1 tumors, such that their size was not different from the smaller PyMT tumors." (PMID 27000374, 2016). "We selected five genes, SPP1, COL1A1, NT5E, HTRA1 and ANGPT1, of 15 genes whose coding proteins could be secreted from the pituitary, and we examined their tumor expression in 118 CD patients." (PMID 27690016, 2016). "The PanCancer pathway panel includes multiple collagen genes and our data also showed significantly higher expression of COL11A1, fold change 24.99, p = 0.001, COL5A1, fold change 3.91, p = 2.0x10-8 and COL1A1, fold change 8.40, p = 5.65x10-8 in ILC tumor relative to adjacent normal tissue." (PMID 27078887, 2016). "On the other hand, the expression of FGF2, as well as CXCR4, CD45 and COL1A1, in the isolated fibrocyte-like cells was similar between the tumours, suggesting that the increase of FGF2 in bevacizumab-treated tumours was due to the increase in the number of these cells." (PMID 26635184, 2015).
tumor (continued). "Comparing the osteogenic potential between these cell lines, LNCaP-19 exclusively has a basal expression of osteoblast-cadherin (CDH11), collagen 1a1 (COL1A1) and osteopontin (Opn, SPP1), all vital genes for tumor interaction with osteoblasts and osteoblastic activity." (PMID 24292404, 2014). "Interestingly, we also found significantly increased and coordinated up-regulation of COL1A1 and COL1A2 in the tumor tissue, both of which are important in blood vessel development." (PMID 24321518, 2013). "Interestingly, our novel findings concerning expression levels of CXCL9, IL8, MMP1, MMP3 and COL1A1 are the converse of previously reported results: CXCL9 protein can modulate host cell infiltration and tumor behavior." (PMID 23405235, 2013). "Analysis of gene expression by quantitative real-time RT-PCR in indirectly co-cultured CCD-1068SK fibroblasts revealed that tumour cells did not influence the expression of COL1A1, COL1A2, CCN2 or Smad7 when compared to fibroblast monocultures." (PMID 24090133, 2013). "Given the role of TGF-β signaling in carcinogenesis, tumor invasion and metastasis via targets like PAI-1 and Col1a1, our data suggest a model on how this effect of ΔNp73 could be a contributing factor in cancer progression." (PMID 23236396, 2012). "Up-regulated genes such as COL1A1, COL1A2, PGF or TGFB1, suggested an important role of these compartment in blood vessel formation, angiogenesis, permeability and invasiveness, essential functions in tumour progression." (PMID 20735813, 2010). "Common up-regulation of genes such as COL1A1, COL1A2, PGF, LRRFIP1, TMEFF2 or TGFB1 suggested an important role of this pool of cells in blood vessel formation, angiogenesis, permeability and proliferation pathways, essentials functions in tumour progression." (PMID 20735813, 2010). "Both COL1A1 and PLAT have been found to increase the proliferation of tumour cells." (PMID 19200380, 2009). "Additionally, COL1A1 and FBLN1 were previously used as markers for canine tumor or fibroblast cells, and MMP2 and DCN as markers of mesenchymal-like cells in human cancers, with the latter also being a top differentially expressed gene in our canine STS sample." (PMID 41208961, 2025). "However, despite beliefs that COL1A1 would also contribute to tumor progression, this has not been confirmed in iCCA where this role has been reported for hyaluronic acid but not COL1A1." (PMID 39858054, 2025). "The spatial localization of HYP peptides for COL1A1, COL1A2, COL5A1 and COL3A1 exhibited distinct region-specific patterns in dormant D-HEp3 compared to awakened P4HA2-depleted D-HEp3 cells, suggesting differential regulation of collagen hydroxylation across tumor zones." (PMID 40671813, 2025). "Moreover, analysis of paired tumor and normal tissue samples showed no significant differential expression of COL1A1, PDGFRB, and SPARC." (PMID 41040657, 2025). "However, in UCEC, dysregulation of COL1A1, ITGB1, THY1, and PDGFRA may compromise immune function, enabling tumor progression." (PMID 40817072, 2025). "A group of genes, including collagen type I alpha 1 (COL1A1), fibronectin 1 (FN1), laminin subunit gamma 2 (LAMC2), periostin (POSTN), transforming growth factor beta induced (TGFBI), are involved in extracellular mesenchymal organization and affect tumor behavior, akin to our findings." (PMID 40303998, 2025). "To begin to determine what might be the role of CCN1 expression by CAFs, we used CAF single-cell expression data to identify a group of six genes (PDGFRA, COL1A1, DCN, TAGLN, COL6A3, and LPAR1) that strongly correlated with CCN1 expression, yet were minimally expressed in other tumor cell types." (PMID 38363129, 2024). "We found that the interactions between COL1A1+ CAFs and tumor cells and Scissor+ tumor cells were mainly mediated by collagen, including COL1A1‐SDC1, COL1A2‐SDC1, COL4A1‐SDC1, COL4A2‐SDC1, COL6A2‐SDC1, and COL6A2‐SDC1, especially Scissor+ tumor cells had stronger interaction with COL1A1 + CAFs." (PMID 37021816, 2023).
tumor (continued). "Analysis of a large genomic patient dataset revealed that the SLRPs lumican, fibromodulin and decorin as well as COL1A1 and COL6A1 all correlate with good overall survival in SHH MB patients; suggesting that the presence of this ECM shell in SHH tumours may be a reliable biomarker of good outcome." (PMID 36631900, 2023). "Furthermore, the gene expression levels of COL1A1 with SDC1, COL1A2 with SDC1, and COL6A3 with SDC1 were significantly positively correlated in TCGA-BC and TCGA-PDAC, supporting their potential interaction in the surrounding tumor niche." (PMID 38002057, 2023). "In co-culture system of ITGA2 knock-down tumor cells and COL1A1 silenced TAFs, the transcription of CTGF and CYR61 was dramatically reduced in ITGA2-depleted cells, whereas, it was elevated in co-cultured with TAFs and markedly decreased after being treated with the COL1A1 inhibitor." (PMID 35322024, 2022). "Notably, we did not observe any ectopic activity by expression of Col1a1;Cre recombinase in tumour endothelial cells." (PMID 35654839, 2022). "Moreover, COL1A1-mediated YAP-signaling activation might be the mechanistic link between TAF and tumor cells with increased transcriptional diversity." (PMID 35322024, 2022). "However, a major remodeling of the tumor mesenchymal phenotype in response to inhibition of Col1a1 has not been described earlier." (PMID 35750880, 2022). "However, much like was observed for the Wnt/β-catenin signaling pathway, neither Lox, Col1a1, Tgfβ, nor NF-κB mRNA levels were significantly impacted by Selenof-genotype in tumor tissues of AOM/DSS-treated WT and Selenof-KO mice." (PMID 34638991, 2021). "The secreted proteins CCL2, TNFRSF21, PLC, COL1A1, PlGF, PAI and IL-6 are all known to be involved in cancer progression and have pro-tumorigenic properties, suggesting that cancer cells can be shifted towards a more aggressive state by tumor microenvironmentally induced secretion." (PMID 34090457, 2021). "Dysregulation of COL1A1 in RCC may be related to epigenetic activation, as COL1A1 has been reported to display promoter methylation in RCC tumor cell line DNA, but not in normal cell DNA." (PMID 34598322, 2021). "However, we observed that optiCA1 overexpressing tumor cells, when compared with the controls, had not statistically changed expression profile of mRNAs (COL1A1, COL4A4, LAMC2, CTHRC1, and WNT7B)." (PMID 31963697, 2020). "The relative expression of COL1A1, IGF1, COL5A1, CXCL12, and PTEN in tumor samples was significantly lower compared to those in adjacent normal samples (P < 0.05), while SPP1 expression was significantly higher in tumor samples compared to the adjacent normal samples (P < 0.05)." (PMID 32641130, 2020). "Besides FLNC, ITGA2, COL1A1 and COL11A1 were tumor invasion and metastasis-related proteins." (PMID 27626164, 2016). "This might be why COL1A1 expression in the tumor is usually higher than that of adjacent noncancerous liver tissue." (PMID 24552139, 2014). "However, in the present study, due to the big overlap of FOXL2 and COL1A1 staining, we could not make a clear separation between tumor and stromal areas." (PMID 41042551, 2025). "Also, in microarray data, collagen, type I, alpha 1 (COL1A1) gene an important fibroblast marker gene was equally expressed (q value=0.99) in both NOSC and HOSC, which clearly indicated that isolated stromal cells from both normal and tumor stromal tissue were stromal fibroblast cells." (PMID 39342193, 2024). "Therefore, we postulated that CAFs positive for FAP in combination with any other marker but negative for COL1A1 might be a tumor‐promoting myCAF population." (PMID 39563958, 2024). "For example, gene expression levels of COL1A1, COL6A3, and FN1 in CAFs as well as COL4A1 and COL4A2 in Angiogenic_EC were correlated with the proportion of the Cancer_Malig subtype in BC and CRC, indicating these pEMT tumor cells might be regulated by COL1A1 in CAFs and COL4A1 in Angiogenic_EC." (PMID 38002057, 2023).
tumor (continued). "However, there was a negative correlation for COL1A1 in five of the 33 tumor types." (PMID 36032075, 2022). "In addition, we hypothesized that if the expression of COL1A1 or relative pathways were inhibited, CD8+ T cells might be enriched in the tumor microenvironment, and the number of CAFs, macrophages, and the PD-L1 expression level might decrease, resulting in attenuated immunoresistance." (PMID 34395525, 2021). "Moreover, as a tumor promoter in EC, circ_0004370 could greatly promote the cell viability, cloning, migration, and invasion, remarkably suppressed apoptosis, and affected EMT process of EC through regulation of miR-1301-3p/COL1A1 axis." (PMID 33506107, 2021). "Thus, the up-regulation of COL1A1 and down-regulation of NCAM1 expression could not only distinguish between cancer and normal tissues, but also divide the cancer patients into different tumor stages." (PMID 25860484, 2015). "However, for this study, we classified all collagen-rich areas as a single histologic category, reasoning that COL1A1+ fibromatous tumors may exhibit behavior more similar to stromal areas with FOXL2+ cells of any kind than to pure tumor regions without collagen." (PMID 41042551, 2025). "Surprisingly, despite the absence of NOX4 in stromal cells, tumours from WT and NOX4-/- mice were identical in size and in the expression levels of Krt19, α-Sma (Acta2) and collagen 1 (Col1a1)." (PMID 40820091, 2025). "We also observed a stepwise increasing deposition of collagen, especially Col1, in ECM from normal liver, non-tumor cirrhotic liver, cirrhotic peri-tumor liver to HCC tissues by Sirius red staining and IHC staining of COL1A1." (PMID 38388466, 2024). "Conversely, injection of EO771 cells into Tyro3flox/flox and Col1a1-cre+;Tyro3flox/flox C57BL/6J mice led to slightly increased hind limb tumor load, whereas tumor load in the later timepoint was not changed." (PMID 36509738, 2022). "However, reducing tumour collagen production by deleting Col1a1 in αSMA-expressing cells or upon treatment with anti–lysyl oxidase like-2 antibody accelerated progression of pancreatic cancer, suggesting that a collagen-rich ECM may also have tumour-protecting functions." (PMID 35760868, 2022). "On the contrary, we observe upregulated oncogene like COL1A1, COL3A1, and downregulated miRNA, which did not correlate with downregulated collagen in vivo in treated tumour samples (data not shown)." (PMID 35615145, 2022). "Most importantly, however, quantification of the tumor cell area did not identify a significant difference between NSG mice and Col1a1-Krm2-transgenic NSG mice, even if all mice were included in the statistical analysis." (PMID 35158823, 2022). "Focusing on tumor samples, we did not observe a clear stratification according to the tumor histotype, even though high LOX and COL1A1 levels were detected in ATCs." (PMID 31906302, 2020). "All 22 cases presented COL1A1-PDGFB rearrangement and none had received imatinib before tumor sampling." (PMID 29492209, 2018). "Compared to non-treated mouse tumours, macrophages in CT-treated tumours showed significant upregulation of phagocytosis genes such as Stab1, Mrc1, Mertk and downregulation of ECM and angiogenesis such as Mmp9 and Col1a1." (PMID 39578450, 2024). "Although our quantitative analysis revealed a large heterogeneity in the volume occupied by tumor cells, the quantification of the tumor area did not reveal significant differences between NSG mice and Col1a1-Krm2-transgenic NSG mice, also not at the level of individual vertebral bodies." (PMID 35158823, 2022). "The demonstration of CSC-expression and secretion of Col1A1 independent of fibroblasts or pancreatic stellate cells, and DEspR+ CSC-derived tumor microvessels in vivo, suggest CSC self-sufficiency in orchestrating tumorigenesis and progression in the peritoneal space." (PMID 33853558, 2021).